VCAN (versican)
Diseases named in the same sentence as VCAN in open-access papers (continued):
Sharing a sentence is not in itself a finding about the gene and the disease.
Wagner syndrome (17 papers, 2010 to 2025). "COL2A1 and COL11A1 were responsible for Stickler syndrome (15%, 6/40) and VCAN was associated with Wagner syndrome (5.0%, 2/40)." (PMID 40270540, 2025). "Erosive vitreoretinopathy is believed to be an allelic variant of Wagner syndrome caused by more severe functional disruption of versican or related pathways which can be modulated by modifier genes or environmental factors." (PMID 40747364, 2025). "Wagner syndrome is a rare autosomal dominant vitreoretinopathy caused by mutations in chondroitin sulphate proteoglycan 2 (CSPG2)/Versican (VCAN)." (PMID 39336769, 2024). "Wagner syndrome is caused by genetic changes in the VCAN gene (previously named CSPG2), which encodes Versican protein, a chondroitin sulphate proteoglycan-2 found in the vitreous among other tissues." (PMID 39202371, 2024). "Specifically, versican mutations underlie Wagner syndrome, a rare disease characterized by several ocular changes, including vitreopathy, myopia and cataracts." (PMID 39180052, 2024). "It is an extremely rare disease, with not much more than 250 patients having been described to date (together with another disease due to mutations in the VCAN gene-erosive vitreoretinopathy)." (PMID 39202371, 2024). "Wagner syndrome is caused by pathogenic variants of the VCAN gene encoding Versican, which is expressed in many soft tissues including vitreous." (PMID 35741851, 2022). "Heterozygous variants targeting exon 8 of VCAN have been shown to cause Wagner disease, a rare autosomal dominant non-syndromic vitreoretinopathy that induces retinal detachment, cataracts and permanent visual loss." (PMID 32854301, 2020). "VCAN mutations are known to cause Wagner syndrome (OMIM #143200), an autosomal dominant disease characterized by isolated vitreoretinopathy." (PMID 30740127, 2018). "Nevertheless, mutations in the VCAN gene are known to cause Wagner syndrome (OMIM #143200), a very rare dominant disease-causing vitreoretinopathy." (PMID 30740127, 2018). "Wagner syndrome is mainly due to very rare mutations affecting VCAN isoforms splicing with a dominant inheritance." (PMID 30740127, 2018). "Wagner syndrome is associated with mutations in versican (VCAN), which encodes for a chondroitin sulfate proteoglycan." (PMID 23592912, 2013). "We report a new VCAN splicing mutation causing typical Wagner syndrome vitreous features associated with unexplained intraocular inflammatory manifestations." (PMID 24174867, 2013). "Wagner Syndrome is a rare inherited vitreoretinopathy associated with mutations in the VCAN gene." (PMID 40747364, 2025). "Similarly, mutations in the versican gene are solely responsible for the rare Wagner Syndrome disease characterised by a progressive break down of the retina, highlighting the essential role versican plays in matrix stability and scaffolding." (PMID 34527586, 2021). "Dominant splicing mutations in VCAN are known to cause Wagner syndrome or vitreoretinopathy." (PMID 30740127, 2018). "It has been demonstrated that these splice site mutations responsible for Wagner syndrome lead to skipping of exon 8, yielding an imbalanced quantitative ratio of versican transcripts with an increased amount of V2 and V3 isoforms and haploinsufficiency of V0 and V1 isoforms." (PMID 21738396, 2011). "Therefore, the pathogenic mechanism of Wagner syndrome is thought to result in a reduction of chondroitin sulfate side chains, which affect interactions of versican, with other extracellular components responsible for accelerated pathologic liquefaction of the vitreous gel." (PMID 21738396, 2011). "Versican, the protein affected in Wagner syndrome, is involved in maintaining the composition of the extracellular matrix which is important in the normal structure and function of the vitreous and vitreoretinal interface." (PMID 40747364, 2025).
Wagner syndrome (continued). "Here, we present a retrospective case series of a family pedigree with genetically confirmed Wagner syndrome (heterozygous VCAN exon 8 deletion), as follows: a 34-year-old mother (P1), 12-year-old daughter (P2), and a 2-year-old son (P3)." (PMID 39336769, 2024). "The retinal abnormalities present in our and others’ patients with Wagner syndrome point towards an essential role of VCAN in retinal development and function." (PMID 39336769, 2024). "It is thus clear that in order to understand the pathophysiology of Wagner syndrome, more research is needed to investigate the specific roles that VCAN and its isoforms play in the development and function of the human eye." (PMID 39336769, 2024). "Wagner Syndrome is caused by an AD inherited mutation in the VCAN gene on chromosome 5q, encoding for versican, an extracellular matrix proteoglycan contributing to the structural integrity of the vitreous." (PMID 34501218, 2021). "In this study, we report on six patients from three unrelated families with Wagner disease in whom we identified three novel copy number variations of VCAN." (PMID 32854301, 2020). "Based on these findings, imbalanced versican isoforms were considered as the possible molecular underpinnings of Wagner syndrome." (PMID 32854301, 2020). "We report the first French family with ocular features of Wagner syndrome segregating with a adenine to thymine transversion at the highly conserved splice acceptor site in intron 7 of the VCAN gene (c.4004–2A>T)." (PMID 21738396, 2011). "The disease gene for Wagner syndrome, recently referred to as VCAN, codes for a chondroitin sulfate (CS) proteoglycan termed versican, which belongs to the lectican family of large aggregating chondrotin sulfate proteoglycans." (PMID 21738396, 2011). "Wagner syndrome can be caused by a mutation in the human VCAN gene, which encodes versican, a proteoglycan present in the vitreous body." (PMID 20454693, 2010). "In Wagner syndrome, dysfunction of versican leads to early liquefaction of the vitreous and development of a thickened posterior hyaloid which in turn may lead to an increased risk of retinal detachment." (PMID 40747364, 2025). "Altogether, the clinical inflammatory manifestations in patients with WS and the inflammatory properties of versican contribute to suggest that intraocular inflammation could belong to the clinical spectrum of Wagner syndrome." (PMID 24174867, 2013).
colon carcinoma (16 papers, 2013 to 2023). "The glycoproteins versican and lumican are overexpressed at the mRNA level in colon carcinomas compared to adenomas, and are associated with the formation of tumor stroma." (PMID 28481899, 2017). "The glycoproteins versican and lumican are overexpressed in colon carcinomas and are associated with the formation of tumor stroma." (PMID 22711178, 2013). "The results presented here emphasize that both versican and lumican are associated with colon cancer prognosis." (PMID 22711178, 2013). "Interestingly, we found that VCAN is highly over-expressed in colon cancer and increased expression of VCAN was associated with the progression of colon cancer." (PMID 30237752, 2018). "INHBA enhances the proliferation, migration, and invasion of colon cancer cells by upregulating VCAN." (PMID 35216189, 2022). "Result showed VCAN was significantly up-regulated at the mRNA level in colon cancer samples compared with normal colon tissues." (PMID 30237752, 2018). "To determine the function of VCAN in regulating human colon cancer cell phenotype, we next performed knockdown of VCAN in HCT-116 cell line that with higher VCAN expression using small interfering RNA." (PMID 30237752, 2018). "Immunohistochemical staining analysis in 100 human colon cancers and matched adjacent tissue microarray showed that VCAN was significantly over-expressed in colon cancer samples compared with adjacent tissue." (PMID 30237752, 2018). "Immunohistochemical staining analysis in 100 human colon cancers and matched 60 adjacent tissue microarrays showed that VCAN was significantly over-expressed in colon cancer samples compared with adjacent tissue." (PMID 30237752, 2018). "qRT-PCR analysis were performed to detected the expression profile of VCAN in a panel of colon cancer cDNA arrays including 30 patients with colon cancer and 30 healthy controls." (PMID 30237752, 2018). "Analysis of proteins secreted by carcinoma cells that could influence macrophage phenotype identified the proteoglycan versican (VCAN) in colon carcinoma cell lines." (PMID 31528221, 2019). "Furthermore, VCAN expression levels correlate with tumour progression and are a strong prognostic indicator, particularly in stage II colon cancer." (PMID 31336942, 2019). "To investigate the correlation between VCAN expression and survival of colon cancer patient, we conducted a Kaplan–Meier analysis with TCGA samples dichotomized into 2 groups with expression levels less than or equal to median and levels more than median of expression." (PMID 30237752, 2018). "High VCAN levels also predict shorter overall survival of colon cancer patients." (PMID 30237752, 2018). "We identified versican (VCAN), a member of the aggrecan/versican proteoglycan family, as a key regulator in human colon cancer development and progression involved in cell adhesion, proliferation, migration and angiogenesis and plays a central role in tissue morphogenesis and maintenance." (PMID 30237752, 2018). "Interestingly, genes that are associated with colon cancer progression (ANTXR1, EFEMP2, SULF1, TAGLN, VCAN, ZEB1 and ZEB2) were upregulated in patients co-overexpressing TAZ-AXL-CTGF." (PMID 23372686, 2013). "Another important ECM protein, Versican (VCAN) is known to be up-regulated in a wide range of cancers and has been reported as a strong prognostic marker in stages II and III colon cancer." (PMID 35642021, 2022). "On the other hand, the protein expression of versican and lumican predicted good clinical outcomes for stage III and II colon cancer patients, respectively." (PMID 31531098, 2019). "The aim of the present study was to investigate the potential prognostic value of lumican and versican expression in the epithelial and stromal compartment of stage II and III colon cancer." (PMID 22711178, 2013).
colon carcinoma (continued). "The aim of the present study was to investigate the potential prognostic value of versican and lumican expression in the epithelial and stromal compartment of Union for International Cancer Control (UICC) stage II and III colon cancer." (PMID 22711178, 2013). "Protein expression of versican and lumican predicted good clinical outcome for stage III and II colon cancer patients, respectively." (PMID 22711178, 2013). "In combination with MSI status, versican and lumican are putative prognostic biomarkers that predict good outcome in stage II and III colon cancer patients, and in the latter also with respect to the effect of adjuvant chemotherapy." (PMID 22711178, 2013).
asthma (15 papers, 2006 to 2024). "The involvement of versican in chronic obstructive pulmonary disease, asthma, and bronchiolitis obliterans syndrome have been described, underlining the importance of versican for upholding lung structure and function." (PMID 29728109, 2018). "In central airways we found increased percentage areas of versican and decorin in patients with uncontrolled asthma compared to both healthy controls and patients with controlled asthma." (PMID 24950767, 2014). "In the alveolar parenchyma, patients with uncontrolled asthma had increased percentage areas of collagen, versican and decorin compared to patients with controlled asthma." (PMID 24950767, 2014). "This location is also abundant in fibroblasts and myofibroblasts in the asthma patient, while the proteoglycans, versican, biglycan, and decorin, accumulate in the submucosa below the epithelium in bronchial biopsies from asthma patients." (PMID 21658209, 2011). "Increased versican has been reported for various lung diseases including fibrosis, granulomatous diseases, asthma, and LAM." (PMID 18485243, 2008). "In postmortem lung tissue from patients dying with fatal asthma, hyaluronan, versican, biglycan and decorin were prominently localized in the airway wall." (PMID 16643666, 2006). "In addition, the role of versican has been elucidated in lung disorders including chronic obstructive pulmonary disease and asthma which showed an upregulation of the protein." (PMID 36059933, 2022). "Accumulation of versican, as seen in the central airways of patients with uncontrolled asthma, could also lead to increased stiffness around cells, which in turn can influence their ability to migrate, proliferate, adhere and remodel the matrix." (PMID 24950767, 2014). "Versican, a large aggregating proteoglycan essential for regulating the lung’s viscoelastic properties and decorin, a small leucine-rich proteoglycan that interact with TGF-β and regulate collagen fibril spacing, have both been implicated in increased bronchial tissue remodeling in asthma." (PMID 39068387, 2024). "Other studies showed that the gene and/or protein expression of collagen I, fibronectin, versican, elastin, tenascin C, periostin, and vimentin was increased in ASMC and PF in asthma studies, including in vivo, ex vivo, in vitro, and animal model studies." (PMID 35456903, 2022). "Increased versican deposition has been demonstrated in fibroblastic foci of IPF patients as well as in the lungs of patients with COPD or asthma, suggesting a role in the faulty repair processes related to chronic lung diseases." (PMID 29728109, 2018). "After application of maximal strain, there was increased mRNA expression of key proteoglycans, versican and decorin, in asthma-derived compared to non-asthma-derived bronchial fibroblasts." (PMID 39068387, 2024).
liver fibrosis (15 papers, 2011 to 2025). "VCAN was consistently upregulated across days 3–7, in line with reports of VCAN accumulation during liver fibrosis and stellate cell activation." (PMID 41472116, 2025). "Expression of VCAN was shown to be significantly upregulated in the livers of cirrhotic patients and from animal models of hepatic fibrosis." (PMID 35454809, 2022). "Many of these genes, including COL1A1, LOX, MMP14, TGFB3, TIMP1 and VCAN, are known markers for liver fibrosis." (PMID 34588551, 2021). "In liver fibrosis, for example, published work has shown that both versican and lumican are regulators of fibrogenesis, but they have opposite effects on collagen reorganization." (PMID 33149218, 2020). "This supports the view that DAA-induced eradication of HCV could promote a reversal of fibrosis, and versican-positive microvesicles could be a potential early biomarker of liver fibrosis." (PMID 34065048, 2021). "It has been hypothesised that versican could have a pro-inflammatory effect in liver fibrosis as both the intact molecule and products of tissue remodeling by proteases are overexpressed in patients with advanced fibrosis." (PMID 33262757, 2020). "Versican is suggested to play a role in liver fibrosis by activating HSCs in in vitro experiments." (PMID 33262757, 2020). "Augmented expression of versican in the CCl4-induced liver fibrosis has been observed." (PMID 27547834, 2016). "While only scarce information is available about versican in fibrosis, except in the lung (where it may influence early repair processes), fibulin-1 deposits were already reported in rat liver fibrosis." (PMID 21975223, 2011). "The aberration of versican plays critical roles in fibroproliferative diseases, such as exacerbating degradation of myocardial cells (Heart failure), increasing activation of hepatic stellate cells (Hepatic fibrosis) and thickening tunica intima (Ischemic cerebral small-vessel disease)." (PMID 37626330, 2023). "The upregulated genes including VCAN and ITGAV by HBV-SITE-1 are both novel biomarkers of hepatitis B virus-related liver fibrosis." (PMID 40405227, 2025). "For example, versican expression and its cleavage via multiple ADAMTS enzymes, including ADAMTS5, are dysregulated during liver fibrosis and recovery." (PMID 39510178, 2024). "In a study by Ramnath and colleagues, the authors found V0 and V1 isoforms to be elevated in advanced liver fibrosis from either HCV or fatty liver disease, and these patients had elevated serum levels of versican." (PMID 33262757, 2020). "Concomitantly, the levels of ADAM-TS1, involved in versican proteolysis, were enhanced and higher in liver fibrosis than without steatosis." (PMID 34065048, 2021).